BRAF (B-Raf proto-oncogene, serine/threonine kinase)
Diseases named in the same sentence as BRAF in open-access papers (continued):
Sharing a sentence is not in itself a finding about the gene and the disease.
tumor (5,713 papers, 2003 to 2026). "In our study, we observed increased TIGIT protein levels in BRAF-mutated tumor group compared with the BRAF wild-type CRC tumor group, whereas no similar association was found for CD155 concentrations." (PMID 41596586, 2026). "Activating mutations in BRAF (e.g., V600E) drive tumor proliferation, making BRAF inhibitors like vemurafenib and dabrafenib cornerstone therapies." (PMID 41497266, 2026). "Multiplex immunofluorescence staining demonstrated that BCL-xL inhibition effectively triggered apoptosis in heterogeneous PDX tumor slice models, including models harboring oncogenic BRAF mutations." (PMID 41620400, 2026). "Isolated BRAF positivity demonstrated a sensitivity of 38.8% and a specificity of 96.7% when low-risk neoplasms were classified as benign, with an overall accuracy of 78.2%." (PMID 41595518, 2026). "Its prognostic value is further amplified by large tumor size, with the coexistence of bilaterality and large tumor diameter identifying a distinct high-risk population, exclusively among BRAF-mutant patients." (PMID 42058723, 2026). "Tumor testing revealed microsatellite instability, loss of MLH1 and PMS2 expression, high tumor mutational burden (21.87 mutations/Mb), and wild‐type BRAF." (PMID 41347766, 2026). "As the tumor tested positive for BRAF V600E mutation using the MEBGENTM BRAF kit, combination therapy with dabrafenib and trametinib was initiated." (PMID 42317943, 2026). "A positive correlation was observed between the presence of a BRAF mutation and the right-sidedness of the tumor (p = 0.001) as well as with the presence of microsatellite instability (p = 0.004)." (PMID 41827330, 2026). "High-risk clinicopathological features, such as tumor size >2 cm, extrathyroidal extension, and aggressive histological variants, are discussed alongside molecular markers (BRAF V600E, TERT, RET/PTC) that predict metastatic potential." (PMID 41684449, 2026). "CIBERSORT computational algorithm was also used to quantify the relative abundance of tumor-infiltrating immune cells (TICs), demonstrating that 11 types of activated TICs were strongly associated with BRAF expression." (PMID 41678466, 2026). "NRAS codon 61 mutations were the most common alterations, followed by BRAF V600E, consistent with known molecular patterns in follicular-derived neoplasms." (PMID 41595518, 2026). "Encorafenib (LGX818) is an ATP‐competitive BRAF inhibitor that can inhibit the MAPK pathway in tumor cells expressing various forms of BRAF kinase mutations, such as V600E, V600D, and V600K mutations." (PMID 41492362, 2026). "CRC with wild-type KRAS/BRAF, microsatellite stability, and low tumor mutational burden is generally considered to have a low risk of central nervous system (CNS) dissemination." (PMID 42109661, 2026). "Based on this theory, primary BRAF/EGFR co-mutated patients have a higher propensity to develop dominant BRAF-mutated tumor clones following resistance to EGFR TKIs treatment." (PMID 40242250, 2025). "Studies have shown that the presence of BRAF V600E is associated with more aggressive tumor behavior, such as extrathyroidal extension, lymph node metastasis, and poor prognosis." (PMID 40104288, 2025). "While the BRAF V600E mutation has been historically associated with more aggressive tumor features, its independent clinical utility as a definitive prognostic factor is actively debated." (PMID 41458539, 2025). "On the contrary, HT-29 cells harbor the BRAF mutation, which is associated with a more aggressive tumor behavior." (PMID 40004697, 2025). "Ideally, transcriptomic data would be normalized to adjacent normal tissue; however, we feel that since RNA was assessed similarly in the two tumor types and despite BRAF mutational status, comparisons between groups are valid." (PMID 40869231, 2025).
tumor (continued). "Precision medicine tailors' interventions to the unique genomic profile of a patient's tumor, with actionable mutations like BRAF V600E, identified in related odontogenic carcinomas, serving as potential targets for therapy." (PMID 40336633, 2025). "High TIMP1 serum levels associated with MMR deficient status, high ASA classification, older age, elevated mGPS (all p < 0.001), proximal tumor location (p = 0.032), and BRAF mutation (p = 0.006)." (PMID 39789100, 2025). "In patients with KRAS, NRAS or BRAF mutation and the moderate to strong expression of all three of these proteins in the tumor microenvironment, the number of metastatic lymph nodes was higher than in other patients." (PMID 39857068, 2025). "In LCH and other neoplasms harboring the BRAF-V600E mutation, ERK activation occurs independently of RAS or dimerization, promoting increased cellular survival, proliferation, and differentiation." (PMID 39958088, 2025). "The innovation of this study lies in introducing the concept of mutation abundance, using a continuous variable to reflect tumor heterogeneity and mutational burden, thereby enabling a more refined evaluation of the impact of BRAF mutation on metastasis." (PMID 41228353, 2025). "Some genes exhibit tumour-type-specific patterns, including BRAF, ATRX, and PTEN, where transcriptional signatures of mutation are strong but limited to specific tumour types." (PMID 40775769, 2025). "This aligns with our findings, where all tumours with Class I mutations harboured co-driving BRAF or NRAS mutations." (PMID 40107205, 2025). "Its expression and activity are correlated with tumor invasion, lymph node metastasis, and BRAF mutation status." (PMID 41462994, 2025). "Other pediatric low‐grade tumor types carry a BRAF V600E mutation and vary notably depending on the histology and the location of the tumor." (PMID 40588233, 2025). "Other studies report that positive BRAF V600E expression is associated with the tumour thickness, the presence of ulceration, reduced overall survival, and non-brisk inflammation." (PMID 40507250, 2025). "One class 3–mutant tumor had an additional BRAF mutation, harboring both D594G and a class 2 change, G469V." (PMID 39751654, 2025). "In contrast, it shows a negative correlation with ATRX, a gene linked to TMZ resistance, and also with tumour‐growth‐promoting genes like BRAF and MET." (PMID 40662483, 2025). "From a clinical perspective, for instance, we observed that BRAF mutations occurred in tumours with serrated morphology." (PMID 40302146, 2025). "Even worse, the present study found that elevated Hsp90α/β protein levels, which are co-expressed with its client molecules and tumor drivers BRAF V600E mutated and Her2/neu overexpressed, further impaired the prognosis of CRC." (PMID 40498011, 2025). "BRAF mutations were significantly associated (p<0.05) with factors such as female gender, poor tumor differentiation, high-grade malignancies, and peritoneal metastasis." (PMID 40949797, 2025). "We also conducted univariate and multivariate analyses and found that tumor size and the presence of BRAF V600E and TERT promoter co-mutations were significant predictors of second recurrence." (PMID 40988283, 2025). "This PT was organized by the Taiwan Society of Pathology using a tissue microarray, containing six tumor cores with confirmed BRAF mutation status and one positive control." (PMID 40689945, 2025). "It should be noted that the presence of BRAF mutations has been associated with high-risk clinicopathological characteristics like tumor size, extrathyroidal invasion, lymph node metastasis, and higher TNM stage." (PMID 39744583, 2025).
tumor (continued). "Vemurafenib reduces the tumor size in more than half of advanced BRAF V600E mutation MM patients, while also keeping patients stable." (PMID 39857808, 2025). "Among these, the BRAF inhibitors—vemurafenib (Zelboraf), dabrafenib (Tafinlar), and encorafenib (Braftovi)—have shown remarkable efficacy in patients harboring BRAF V600E/K mutations, producing rapid tumor regression and high initial response rates." (PMID 41302945, 2025). "V600E mutation associated with drug resistance, tumor growth and invasiveness is the most relevant BRAF mutation, occurring in 90% of all BRAF-mutant cases." (PMID 39935431, 2025). "All pLGG tumor subgroups have a documented driver mutation in the BRAF oncogene or within a cooperating protein along the MAPK pathway, namely the RAS, RAF, MEK, and ERK kinases." (PMID 40007996, 2025). "Clinically, BRAF V600E has been associated with more aggressive tumor behavior and a worse prognosis." (PMID 40332392, 2025). "Tumour pigmentation status revealed that levels of 15 metabolites were altered, whereas other features, such as BRAF mutation status, initial site of metastasis and patient sex, did not contribute to metabolic variance in these models." (PMID 40731149, 2025). "While BRAF V600E is typically associated with poor prognosis and increased tumor aggressiveness, evidence suggests that PD-1 blockade can partially overcome its negative prognostic impact in MSI-H/dMMR CRC." (PMID 41346621, 2025). "Molecular analysis of the archival primary tumor tissue revealed the presence of the BRAF V600E mutation." (PMID 39935827, 2025). "Compared with conventional predictors such as ultrasound features (e.g., morphology, margins, microcalcifications), tumor diameter, and BRAF mutation status, this model shows only moderate predictive power." (PMID 41291156, 2025). "Treatment of BRAF PTEN PREX2-GD mice with a MAPK inhibitor caused tumor regression and extended overall survival." (PMID 39636745, 2025). "Two samples with PIK3CA mutations (one with PIK3CA only and one with BRAF V600E/PIK3CA) were confirmed to be one malignant tumor and one benign tumor." (PMID 40586006, 2025). "Overall, these findings suggested that mannose significantly enhanced the anti-tumor efficacy of PLX4032 in BRAF-mutated ATC." (PMID 40063000, 2025). "PLX47206, sorafenib, and dabrafenib have been developed as inhibitors that effectively block the MAPK signaling pathway, reducing tumor growth in cells harboring the BRAF V600E mutation." (PMID 40872623, 2025). "In standard clinical practice, patients are selected for EGFR inhibitors based on RAS/BRAF mutation status and location of the primary tumor." (PMID 40982295, 2025). "The MAPK/ERK pathway typically regulates cell division, differentiation, and apoptosis in normal cells, but in cells with the BRAF V600E mutation, it becomes hyperactive, driving uncontrolled cell proliferation and tumor formation." (PMID 40988283, 2025). "Consistent with our findings, BRAF tumor mutations have been observed to be more prevalent among women." (PMID 41413856, 2025). "The associations between wild-type BRAF, tumour-infiltrating lymphocytes and immune cell composition highlight the importance of a personalized approach to immunotherapy." (PMID 40251644, 2025). "BRAF V600E was found in RET-negative tumours, with novel mutations (G469A and T599dup), suggesting BRAF as a scarce driver of MTC carcinogenesis." (PMID 40332222, 2025). "Ojemda has demonstrated significant rapid and sustained tumor responses in patients with recurrent or refractory pLGG harboring BRAF mutations." (PMID 40430547, 2025). "Using stepwise regression, we ultimately identified seven factors independently associated with CLNM: irregular margins, microcalcifications, lymph node enlargement, lesion group, maximum tumor diameter, BRAF V600E mutation abundance, and age." (PMID 41228353, 2025).
tumor (continued). "A retrospective analysis revealed that NSCLC patients with BRAF V600E mutations (10 cases) had a lower tumor mutational burden (TMB) compared to non-V600E-mutant NSCLC patients (42 cases), and showed a lower ORR to immunotherapy (11% versus 23%, respectively)." (PMID 40896440, 2025). "The study suggested that combining tumor size and BRAF mutation status can refine risk stratification within AUS/FLUS nodules." (PMID 40970023, 2025). "Firstly, we observed that CRC patients with the BRAF V600E mutation exhibited significantly higher immune scores and lower tumor purity compared to wild-type CRC patients, while their stromal scores remained similar." (PMID 39934467, 2025). "BRAF V600E mutation was confirmed in tumor specimens from all patients using the MEBGENTM BRAF 3 kit (Medical & Biological Laboratories Co., Ltd., Japan), which employs polymerase chain reaction with sequence-specific oligonucleotide probes (PCR-rSSO)." (PMID 40844731, 2025). "Based on the ROAR basket trial results, a combination of dabrafenib and trametinib should be considered in all tumours harbouring BRAF p.V600E mutation, including PDAC." (PMID 38773787, 2025). "The metachronous tumor was a moderately differentiated adenocarcinoma with a tumor mutational burden of 58 mutations/megabase and a BRAF V600E mutation." (PMID 41170468, 2025). "These criteria include being younger and having a multifocal tumor with a potentially aggressive molecular phenotype, as indicated by the presence of BRAF and TERT mutations, as well as PD-L1 positivity." (PMID 40650194, 2025). "Tumor shrinkage occurred both in OPGs harboring BRAF fusions and BRAF V600E mutations, and both in patients who had previously received mitogen-activated protein kinase inhibitor (MAPKi) therapy and patients who had not." (PMID 39700439, 2025). "GO and KEGG enrichment analyses demonstrated that these DEGs were primarily enriched in cytokine- and chemokine-related pathways, suggesting a potential role of the BRAF V600E mutation in modulating tumor immunity." (PMID 39934467, 2025). "This review examines the molecular biology of the BRAF V600E mutation, its role in tumor progression, and its utility in the diagnosis, prognosis and treatment of specific types of tumors." (PMID 40977811, 2025). "A short-term follow-up of 3 years was available for 15 patients, 3 of whom had tumor recurrence (all cases in the BRAF-mutated group)." (PMID 40564801, 2025). "Consistent with this, the left-sided tumor in our patient with the BRAF mutation displayed more giant cell features on microscopy, whereas the right-sided tumor did not." (PMID 41473634, 2025). "The differences are unreliable; however, there is a tendency towards a rarer detection of high-risk aberrations in patients with the KRAS, NRAS, and BRAF gene mutations at any tumor locus." (PMID 40943426, 2025). "The BRAF alterations present in the reported patient are associated with better survival in a variety of tumours." (PMID 41573648, 2025). "In this study, SBT/carcinoma pairs showed concordant profiles in 56% of KRAS-mutated tumor cases, 31% of wild-type tumor cases, and only 13% of BRAF-mutated tumor cases." (PMID 40564801, 2025). "NRAS mutations are typically associated with higher rates of mitosis and thicker tumours compared to BRAF V600E." (PMID 40447784, 2025). "In our experience, BRAF V600E IHC is highly useful in highlighting the tumor extent and the unique patterns of invasion (lateral tubular growth and isolated tumor clusters), which are characteristic of BRAF-mutated PTCs." (PMID 40111709, 2025). "CRCs with defective ZNRF3 mutations are highly enriched for BRAF-V600E mutation, a mismatch-repair defect, and right-sided tumor location (41/63, 46/56, and 39/47, respectively)." (PMID 39674817, 2025).
tumor (continued). "BRAF-positive ATCs are thought to arise from pre-existing BRAF-mutated PTCs, as suggested by cases where both tumor components co-exist and share the mutation." (PMID 40332392, 2025). "Extensive studies have established a link between BRAF V600E mutations and increased tumor aggressiveness, including higher rates of recurrence and disease-specific mortality in PTC patients." (PMID 40469184, 2025). "BRAF mutations and their association with patient/tumour characteristics and survival is poorly understood." (PMID 40902091, 2025). "In this preclinical study, we set out to investigate the impact of tovorafenib alone or in combination with MEK inhibitor pimasertib in adult or pediatric tumor models harboring either an AGK::BRAF fusion or an NF1-LOF mutation." (PMID 40111124, 2025). "Reduced expression has been found to be associated with worse survival and several unfavorable prognostic factors, including advanced stage, higher tumor grade, and BRAF mutation." (PMID 39998677, 2025). "Unlike the metabolism of normal cells, which primarily use oxidative phosphorylation in mitochondria to produce energy in the presence of oxygen, tumor cells, including those with BRAF mutation, favor glycolysis even under aerobic conditions." (PMID 40872623, 2025). "We found mucinous differentiation to be associated with proximal colon location, high tumour grade, and BRAF mutation, which are indications of a more aggressive tumour phenotype." (PMID 39966658, 2025). "The tumour harboured a gain-of-function mutation of v-raf murine sarcoma viral oncogene homolog B1 (BRAF) V600E." (PMID 40689241, 2025). "Real-world overall survival (rwOS), defined as the time from the first detection of BRAF mutation in circulating tumor DNA to death from any cause, was evaluated in 813 unique NSCLC patients with BRAF alterations." (PMID 41282105, 2025). "Our analysis revealed that KRAS and BRAF mutations significantly increased the risk of tumor occurrence and death in stage II/III CRC patients." (PMID 40279317, 2025). "In June 2022, the FDA granted accelerated approval to the combination of dabrafenib and trametinib for unresectable or metastatic solid tumors with BRAF V600E mutation, establishing BRAF V600E as a pan-tumor biomarker." (PMID 40576713, 2025). "Metabolomic analysis of tumor tissue showed low levels of vitamin C and its metabolites in BRAF-mutated tumors." (PMID 40102611, 2025). "BRAF V600E mutation-targeting drugs usually develop resistance within 6 months of continued use, diminishing their efficacy and increasing the risk of tumor recurrence." (PMID 39795195, 2025). "Genetic testing revealed that the tumor was a RAS mutated, BRAF wild type, and microsatellite stability tumor." (PMID 40144703, 2025). "Overall, 107 patients with BRAF V600E mutated mCRC (based on analyses of tumor tissue) were included into the full analysis set of the FIRE‐4.5 study." (PMID 39630848, 2025). "Key good prognostic factors for prolonged PFS included having a non-BRAF-mutated tumour, PD-L1 expression ≥1%, and initial metabolic response." (PMID 40419744, 2025). "Oncogenic activation of MAPK signaling, particularly via RAS and BRAF mutations, is known to promote aggressive tumor behavior and confer resistance to EGFR-targeted therapies in CRC patients." (PMID 40227607, 2025). "The prevalence of KRAS and BRAF mutations in proximal tumours from carriers of the rs76011559 minor allele (35% and 19%, respectively) was similar to non-carriers." (PMID 39827162, 2025). "SOX10 loss reduces proliferation but promotes tumor invasiveness and resistance to BRAF and/or MEK inhibitors." (PMID 40866912, 2025). "Random forest and XGBoost consistently achieved strong predictive performances, with studies identifying key risk factors like tumor size, lymph node involvement, age, capsular invasion, and genetic mutations (e.g., BRAF V600E)." (PMID 40282484, 2025).